IL17A (interleukin 17A)
Diseases named in the same sentence as IL17A in open-access papers (continued):
Sharing a sentence is not in itself a finding about the gene and the disease.
tumor (continued). "Given the dynamic tumor immune microenvironment, IL-17A can elicit both cytotoxic and immunosuppressive effects." (PMID 36098359, 2022). "Tumor-derived adrenomedullin activates mast cell degranulation, leading to the release of IL-17a to promote tumor progression." (PMID 35311157, 2022). "γδ T cell derived IL-17A was identified to be highly abundant in the sensitive tumor microenvironment." (PMID 35924165, 2022). "In vivo studies show that IL-17A inhibition at the tumor sites suppressed CD31, MMP9, and VEGF expression in tumor tissues." (PMID 35626056, 2022). "Inhibition of BTNL2 reduces the number of tumour-infiltrating IL-17A-producing γδ T cells and myeloid-derived suppressor cells, while facilitating cytotoxic CD8+ T cell accumulation." (PMID 35017553, 2022). "An observation in OPSCC demonstrated that intra-epithelial B cells interacted with T cells via CXCL9 in the TME, while tumor killing capability of B cells was induced by IL-17A in ESCC." (PMID 34617194, 2022). "Concentration of pro‐inflammatory and pro‐angiogenic cytokines including IL‐1a, IL‐2, IL‐6, IL‐10, IL‐12, and IL‐17A, in peripheral blood of tumor bearing mice receiving anti‐MUC1 nanobody was significantly lower compared to the PBS receiving group." (PMID 34694686, 2022). "In this model, the commensal microbiota drives tumor-associated inflammation (e.g., the recruitment of neutrophils into the tumor microenvironment) and tumor progression through IL-17A expressed by γδ T cells." (PMID 35883573, 2022). "We further analyzed the production of IFN-γ, IL-4, IL17a, and Foxp3 in lymphocytes separated from the tumor tissues, which reflects the population of Th1, Th2, Th17, and Treg cells, respectively." (PMID 36209170, 2022). "Next, we explored the IL-17A-producing cells in the TME, and found that the tumour-infiltrating IL-17A-producing cells were mainly γδ T cells in CT26 and A20 tumours." (PMID 35017553, 2022). "IL17A promotes tumor progression by suppressing anti-tumor immune activity, including its impact on CD8+ T cell polarization to lose their cytotoxic ability." (PMID 35212644, 2022). "(2020) generated a gastric cancer cell line tumor model in mice, performed scRNAseq analysis, and found that successful tumor growth required Il17a in tumor-infiltrating CD4+ Ths." (PMID 35757757, 2022). "As expected, blocking the signal transduction of ERK in CD4+ T cells efficiently attenuated such IL‐17A‐producing Th subset polarization mediated by tumor‐infiltrating neutrophils and TTCS‐conditioned neutrophils." (PMID 34185422, 2021). "Our data revealed that rs8193036 T-allele carriers were associated with significantly more-advanced stages (III + IV) among LUAD patients, suggesting that IL-17A rs8193036 SNPs promote tumor progression probably via upregulation of IL-17A expression." (PMID 33802737, 2021). "More specifically, in the MM microenvironment, IL6 and TGF-β produced by MM cells promote Th17 polarization, while IL-17 (also known as IL17A) produced by Th17 cells promotes tumor progression and MMBD." (PMID 33673480, 2021). "Tumoral neutrophils surpassed non‐tumor tissue neutrophils in inducting IL‐17A‐producing Th subset polarization." (PMID 34185422, 2021). "Mast cells accumulate around tumor cells due to SCFs and degranulate and release cytokines such as IL-17A, affecting tumor progression and fibrosis." (PMID 32488650, 2021). "At 14 days after transplantation, the mean tumor volume increased significantly in the IL-17A-treated group compared with that in the control group." (PMID 32488650, 2021). "Our results revealed a significant upregulation of IL17A within the tumor group when compared to the controls explaining the potential role of FOSL1 in the immune response." (PMID 33801021, 2021).
tumor (continued). "High-dose VEGFR2-TKI treatment induced IL17A production by tumor-infiltrating γδ T cells through the VEGFR1-PI3K-AKT pathway, while IL17A promoted “N2” neutrophil polarization, driving immunosuppression and conferring resistance to anti-VEGFR2 treatment." (PMID 34721375, 2021). "In a mouse fibrosis model, intraperitoneal administration of IL-17A promoted tumor growth and intratumoral fibrosis." (PMID 32488650, 2021). "For example, IL-8 and IL-17A are inflammatory factors that can be secreted by the tumor microenvironment or malignant cells and attract neutrophils to tumor niches." (PMID 35008790, 2021). "In pancreatic ductal adenocarcinoma, esophageal squamous carcinoma, and hepatocellular carcinoma, IL-17A-producing mast cells infiltrate the tumor stroma." (PMID 32488650, 2021). "Neutrophil recruitment by IL-17 in the tumor microenvironment can become a source of IL-17A and promote GC invasiveness." (PMID 33924897, 2021). "Next, we compared the expression levels of IL-17A and miR-15b-5p in tumor tissues between patients with MSS and patients with MSI-H CRC." (PMID 33462141, 2021). "Interleukin-17A (IL-17A), part of the IL-17 family, is a pro-inflammatory cytokine increasingly recognised in tumour initiation and growth." (PMID 34944729, 2021). "IL-17A enhanced tumor growth in vivo via induction of IL-6, activating oncogenic transcription factor STAT3 and stimulating pro-survival and pro-angiogenic tumor genes." (PMID 35008550, 2021). "Compared with the functions of RORγ agonists-untreated cells, the function of CAR Type 17 cells was elevated when reactivated against a series of tumor cell lines expressing mesothelin and secreted more cytokines, including IL17A and IFNγ." (PMID 33752691, 2021). "The role of IL-17A in cancer is thought to correlate with tumorigenesis, tumor proliferation, and angiogenesis." (PMID 32488650, 2021). "MiR-21 knockout mice which received AOM/DSS presented a reduction of neoplasms size and numbers and induced inflammatory and carcinogenic cytokines such as IL-6, IL-17A, IL-21, and IL-23." (PMID 33921348, 2021). "Increased numbers of FOXP3+ lymphocytes, higher IL17A, lower IL2 and a principal component involving Ki67 and macrophages were independently associated with worse outcome in the tumor compartment." (PMID 33648463, 2021). "In previous cancer studies, it was determined that anti-VEGF resistance is driven by IL-17A secreted by tumor resistant cells." (PMID 34456740, 2021). "IL-17A is a protumoral cytokine promoting the recruitment of myeloid-derived suppressor cells (MDSCs) to the tumor bed." (PMID 34868026, 2021). "In ApcF/F and Cdx2-Cre (CPC-Cre) mice, a spontaneous mouse CRC model, the expression of Il17a mRNA was lower in both tumor and normal tissues from ABX-treated mice than in tissue from control mice." (PMID 33578830, 2021). "Dynamic differentiation of IL-17A-expressing T cells in the tumor, due to the presence of particular mediators, such as IL-2, RANTES, or MCP-1, has been demonstrated." (PMID 34944746, 2021). "For example, administration of 5-fluorouracil (5-FU) provokes tumor-promoting inflammatory responses, but the neutralization of cytokines, such as IL-17A, enhances treatment responsiveness." (PMID 34063828, 2021). "We demonstrated IL-17A-producing mast cells correlated with tumor fibrosis, and elucidated that IL-17A induced CAFs from mesothelial cells in vitro and is involved in tumor fibrosis in vivo." (PMID 32488650, 2021). "On the other hand, MKN-45P with IL-17A inoculated group showed large tumor invaded into intestinal tract." (PMID 32488650, 2021). "More research is needed to understand the benefits/harms of Th17/IL17a in the tumor environment and their role in tumor progression." (PMID 33987094, 2021). "Interleukin-17A (IL-17A) is prevalent in various tumor tissues and suppresses tumor immune surveillance." (PMID 32488650, 2021).
tumor (continued). "Despite the relatively small sample size, there is a clear indication that IL-17A production by tumour antigen-specific T cells has a positive influence on anti-tumour immunity, warranting further investigation." (PMID 33674735, 2021). "Their antitumor effects are mediated by direct tumor cell killing via secreting interferon (IFN)-γ but they can also secret IL17A to promote tumor growth." (PMID 34721375, 2021). "Our study supports the associations of tumor FOXP3/CD3 ratios, IL17A and IL2 with outcome in the rituximab era." (PMID 33648463, 2021). "Pre-operatively, circulating neutrophil counts were found to correlate with increased tumor burden, as well as with increased levels of the neutrophil-mobilizing cytokines, interleukin (IL)-1β, IL-17A and tumor necrosis factor-α (TNF-α)." (PMID 34168563, 2021). "The expression of Smad7 in T cells led to an increase in the number of tumor-infiltrating T-bet/RORγ-t double-positive CD4+ T cells while decreasing the expression of IL-17A in CD+ T cells." (PMID 34059951, 2021). "Now our findings support a new notion that neutrophils exposed to tumor‐derived TNF‐α that activates signals associated with B7‐H2 expression, have displayed a potential to generate inflammatory IL‐17A‐producing Th subsets in GC milieu." (PMID 34185422, 2021). "Further detection of tumor infiltrating γδT cells showed that low dose VEGFR2-TKI with YS-49 increased IL17A secretion, while high-dose VEGFR2-TKI with Copanlisib had the opposite effect." (PMID 34721375, 2021). "Given the roles of Th17 and Th22 cells in promoting tumor development, IL-17A, IL-17F, and IL-22 are also promising targets in CRC." (PMID 34489941, 2021). "IL17A exerts its tumor-promoting activity through its type A receptor (IL-17RA), which is expressed in various cell types in the tumor microenvironment, including hematopoietic cells, fibroblasts, and epithelial cells." (PMID 34367971, 2021). "IL-17A has also been shown to enhance the infiltration of MDSCs into tumor tissues and activate their immunosuppressive activity." (PMID 34885241, 2021). "Other studies also suggest that T cells gamma delta can stimulate the production of interleukin-17A (IL-17A), thereby stimulating tumor cell proliferation, inducing angiogenesis and promoting inflammation." (PMID 35127491, 2021). "Earlier studies reported that IL-23 via its effector molecule IL-17A induces the self-renewal ability of tumor cells." (PMID 34680308, 2021). "Among total IL-17A+ cells, 43% and 17% were double positive for PlGF in the stroma and within the tumor masses, respectively." (PMID 34944746, 2021). "Meanwhile, we analyzed the expression of IL-17A, miR-15b-5p, and PD-L1 in each mouse tumor tissues and found that the expression of IL-17A and PD-L1 was decreased and the expression of miR-15b-5p was enhanced in the combined treatment group." (PMID 33462141, 2021). "When a scatter plot was created with length and number of the HCC nodules to present tumor growth patterns, significantly alleviated tumor growth was found in anti-IL-17A treated mice compared to the untreated mice." (PMID 32929325, 2020). "Together, our results reveal a novel role of tumor-derived IL-17A in potentiating the therapeutic effects of MDSC depletion in attenuating 4T1 tumor growth and metastasis." (PMID 32770025, 2020). "In a patient-derived GBM preclinical model, IL-17A inhibitors increased overall survival and decreased tumor growth/tumor hypoxia, angiogenesis, VEGF expression, cell proliferation, leptin expression and adipogenesis compared to control samples." (PMID 33316976, 2020). "It has been shown that IL-17A accelerates PanIN progression through crosstalk of immune cells with tumor cells." (PMID 32210079, 2020). "Interleukin (IL)-17A is a pro-inflammatory cytokine that has both pro- and anti-tumor effects and found in 40–80% of TNBC samples." (PMID 32770025, 2020).
tumor (continued). "Of note, the animal studies showed that PM2.5-enhanced tumor growth was clearly abolished by IL-17a knockout in the established tumor xenograft models." (PMID 32554855, 2020). "Depletion of the lung commensal microbiota in tumor bearing mice led to decreased γδ T cell abundance and IL-17A levels in BALF and serum." (PMID 33375062, 2020). "We injected the antibodies weekly to ensure IL-17A/IL-17RA axis inhibition throughout tumor development and progression." (PMID 32210079, 2020). "Using a murine 4T1 TNBC model, we further demonstrated that ectopic IL-17A expression by tumor cells enhanced 4T1 tumor growth and metastasis." (PMID 32770025, 2020). "IL-17A also promotes the tumor microenvironment formation by attracting an infiltration of immune cells." (PMID 32765487, 2020). "Beyond oxidative stress, myeloid cells are a crucial source of inflammatory cytokines, which can support the survival and proliferation of neoplastic cells (e.g., IL-6, IL-1, IL-23, IL-17A) or the activation of adaptive anti-tumor immunity (e.g., IL-12, IFNγ)." (PMID 32962159, 2020). "IL-17A seems to be an especially promising biomarker because its presence is significantly correlated with stage of disease as well as with primary tumor size with lymph node involvement being considered separately." (PMID 32855976, 2020). "Remarkably, IL-17A expression by tumor cells markedly potentiates the treatment efficacy of anti-Gr1-mediated and anti-G-CSF-mediated MDSC depletion therapies that are otherwise not effective in preventing lung metastasis in 4T1 tumor-bearing mice." (PMID 32770025, 2020). "Despite the expression of IL-17RA and IL-17RC on 4T1 TNBC tumor cells, 4T1 cells transduced with AdIL-17A and Addl showed similar growth kinetics in vitro, suggesting that IL-17A stimulation has a little direct effect on the growth of 4T1 TNBC cells." (PMID 32770025, 2020). "Accordingly, IL-17A–IL-17R pathway inhibition led to a reduced tumor-specific T cell response, underscoring a significant role for γδ T17 cells in anthracycline-induced immunity." (PMID 32340275, 2020). "Our results showed that the accumulation of CD8+ T cells in advanced-stage tumor was systematically inhibited by Th17 cells via IL-17A/STAT3/CXCR3 axis." (PMID 32503584, 2020). "The changes in T cell cytokines produced in the tumor microenvironment following G-CSFR−/− cell injection led us to test the ability of IFNγ or IL-17A alone to inhibit tumor growth." (PMID 33042110, 2020). "Stimulating effect on angiogenesis was also reported in 4T1 tumor model after treating mice with recombinant IL-17A." (PMID 32257539, 2020). "For example, IL-17F is involved in mucosal host defence; IL-17E was confirmed to be an amplifier of TH2 immune responses, and IL-17A shows the highest involvement in tumour progression (including CRC), as well as inflammation and autoimmunity." (PMID 32760201, 2020). "qPCR analyses showed that their absence correlated with IFN-γ (decreased) and IL-17A (increased) detection in tumor tissues." (PMID 32053875, 2020). "Relationship between the percentage of Th17 cells in PB, PF, and tumor and concentration of IL-17A and clinicopathological characteristics of OC patients are shown." (PMID 32148497, 2020). "Similar results were seen with both tumor models in WT mice where either IFNγ or IL-17A significantly decreased tumor size." (PMID 33042110, 2020). "Recent evidence suggests that IL-17A modulates the tumour microenvironment via recruitment of immune cells, including myeloid-derived suppressor cells (MDSCs), Th17 cells and neutrophils." (PMID 32415115, 2020). "The induced iTh17 cells from splenocytes of young mice treated with PRI-2191 expressed significantly higher levels of Il17a mRNA as compared to iTh17 splenocytes from control tumor bearing mice." (PMID 32257539, 2020).
tumor (continued). "In the 4T1 mouse model (young mice), in which PRI-2191, and less clearly also calcitriol increased iTh17 IL-17A secretion, we also observed an increase in blood perfusion within the tumor." (PMID 32257539, 2020). "IL-17A suppressed the infiltration of CD8+ T cells in tumor tissues, which was attenuated by Stattic." (PMID 32503584, 2020). "CD8+ T cell infiltration in advanced-stage tumor was systematically inhibited by Th17 cells via IL-17A/STAT3/CXCR3 axis." (PMID 32503584, 2020). "In hepatocellular carcinoma and fibrosarcoma, the presence of IL-17A increases tumor progression through the development of angiogenesis and metastasis." (PMID 32855976, 2020). "CXCL5 also influences the development of an inflammatory TME by regulating the infiltration of MDSCs in HCC tumor sites via elaboration of IL-17A in γδ T cells." (PMID 33718121, 2020). "Our previous study suggests a promoting effect of IL-17A on tumors 5, whereas other studies suggested its protective role in cancer by enhancing immune system-mediated tumor rejection." (PMID 32489459, 2020). "Here, aged lung γδT cells with predominant production of IL‐17A directly exerted their higher cytotoxicity to tumor cells." (PMID 31903715, 2020). "Increasing studies have shown the importance of IL-17a in promoting tumor development, including NSCLC, via multiple mechanisms." (PMID 32554855, 2020). "According to the IRS and positive rate, CRC patients with high levels of IL-17A in tumor tissues had a poor prognosis." (PMID 32503584, 2020). "In cancer studies, it was determined that anti-VEGF resistance is driven by tumor-secreted factors, and that IL-17A was the most abundant protein secreted by tumor resistant cells." (PMID 32429598, 2020). "IL-17A has been shown to have the ability to both increase tumor progression by activating angiogenesis and immunosuppressive activities, and inhibit tumor progression, through recruitment of immune cells into tumors and stimulation of effector CD8+ T cells." (PMID 32295632, 2020). "Tumour associated neutrophils (TANs) induce EMT in gastric epithelium by the release of IL-17a and activation of IL-17a/JAK2/STAT3 signaling (pathway 6)." (PMID 32899442, 2020). "The HCC nodule number and tumor size were significantly alleviated by treatments of anti-IL-17A antibody." (PMID 32929325, 2020). "We evaluated the plasma concentrations of Th1 (IL-2, IFN-γ, and TNF-α), Th2 (IL-4, IL-5, IL-6, and IL-10), Th9 (IL-9), and Th17 (IL-17A, IL-17F, IL-21, and IL-22) cytokines in tumor-bearing mice by flow cytometry." (PMID 32802733, 2020). "Il17a and Il17re have similar pattern of expression: calcitriol decreased the expression in young mice in the early phase of tumor progression, whereas in old OVX mice the expression of both genes increased." (PMID 32257539, 2020). "As a pro-inflammatory cytokine, Interleukin 17A (IL-17A) plays an important role in pathology of tumor microenvironment and inflammatory diseases." (PMID 32489459, 2020). "Here, we found that administration of either IFNγ or IL-17A at biologically relevant concentrations was effective at reducing tumor growth, concurrent with supporting a cytotoxic immune response." (PMID 33042110, 2020). "Gene expression analyses on human samples will define potential correlates between tumor immune infiltrate and expression of both IL-17A and IL-17D." (PMID 33244315, 2020). "In mouse tumor cell lines expressing the IL-17R, IL-17A induced IL-6 production, which in turn activated signal transducer and activator of transcription (Stat) 3, eventually upregulating pro-survival and proangiogenic signals." (PMID 33244315, 2020). "The lower tumor development in mice harboring TGF-β-DNR CD4+ T cells correlated with a reduced frequency of IL-17A+IL-22+ CD4+ T cells, whereas IL-17A-IL-22+ CD4+ T cells were unaffected." (PMID 32451418, 2020).